MMP3 (matrix metallopeptidase 3)
Diseases named in the same sentence as MMP3 in open-access papers (continued):
Sharing a sentence is not in itself a finding about the gene and the disease.
inflammation (16 papers, 2012 to 2025). Aberrant reaction of the microcirculation characterized by movement of fluid and leukocytes from the blood into extravascular tissues. "Etarfolatide imaging, indicating the presence of activated macrophages and neutrophils in the synovial tissue, provided additional in vivo evidence for synovial inflammation that was positively associated with SF biomarkers MMP-3 and sVCAM-1." (PMID 31196179, 2019). "In contrast, the role of WNT signaling in lung inflammation is largely unexplored, although the canonical pathway activator WNT-1 is implicated in lung inflammation by being linked to stimulation of pro-MMP3 transcription." (PMID 22846383, 2012). "We hypothesized that Nano-CuO exposure would cause elevated expression of MMP-3, which further contributed to the development of lung inflammation, injury, and fibrosis." (PMID 39030581, 2024). "Macrophages play a critical role in synovial inflammation, and their interaction with FLSs results in elevated levels of IL‐6 and MMP‐3, findings that are consistent with our observations." (PMID 40985312, 2025). "Knocking down MMP-3 in mouse lungs significantly attenuated Nano-CuO-induced acute and chronic lung inflammation and fibrosis." (PMID 39030581, 2024). "Several studies have indicated that serum MMP-3 levels significantly correlate with the levels produced by the synovium and thus reflect synovial inflammation and cartilage turnover in inflammatory joint diseases." (PMID 37629227, 2023). "It has already been shown that MMP-3 is involved in liver inflammation, degradation of normal ECM, and release of cytokines that initiate macrophage and leukocyte infiltration." (PMID 35529854, 2022). "In summary, our data provide the first evidence of MMP-3 as a strong modulator of acute ocular inflammation in the posterior part of the eye." (PMID 27809288, 2016). "Our study suggests that MMP-3 may play important roles in Nano-CuO-induced pulmonary inflammation and fibrosis via cleavage of OPN and may provide a further understanding of the mechanisms underlying Nano-CuO-induced pulmonary toxicity." (PMID 39030581, 2024). "Moreover, it was reported that MMP-3 has anti-inflammatory effects in pulpal inflammation and plays a critical role in the angiogenesis and pulp wound healing of injured pulp tissue." (PMID 31771293, 2019). "Therefore, it can be hypothesized that, following chronic synovial inflammation, MMP3 secreted from the synovium may induce degradation of the cartilage in the MMx-induced KOA model, similar to that in human KOA." (PMID 32164328, 2020). "Previous studies demonstrated that OPN plays an important role in pulmonary inflammation and fibrosis, and OPN is a substrate of MMP-3, which cleaves OPN to be a bioactive OPN fragment (40 kDa, N-terminal fragment)." (PMID 39030581, 2024). "While these findings establish the role of MMP-3 and MCP-1 in IRI-induced pulmonary inflammation, our study is the first to demonstrate that apigenin significantly suppresses MCP-1 expression, highlighting its potential therapeutic role in mitigating remote pulmonary inflammation." (PMID 40429525, 2025).
neurodegenerative disease (6 papers, 2013 to 2024). A disorder of the central nervous system characterized by gradual and progressive loss of neural tissue and neurologic function. "Accordingly, these findings add a valuable contribution to the limited body of literature associating this variant to the presence of IVD degenerative disease, and further highlight the importance of MMP-3 in the aetiology of this disease." (PMID 39287911, 2024). "While available literature is limited, the MMP-3 rs63248 variant has been shown to play an integral role toward spinal bone mineral density and degenerative disease." (PMID 39287911, 2024). "On the other hand, in certain neurodegenerative diseases such as AD and MMPs, and, in particular, MMP-3 and MMP-9, were shown to degrade Aβ plaques, justifying the view of MMPs as a double-edged sword." (PMID 26538832, 2015). "Increasing evidence suggests that MMP-3 plays an important role in the pathogenesis of neurodegenerative diseases such as Alzheimer's disease, vascular dementia, ischemic stroke, and PD." (PMID 23853428, 2013). "More than a dozen MMPs were shown to be involved in neurodegenerative diseases, including MMP-2, MMP-3, and MMP-9, and they seem to be important players in most of the diseases mentioned in this review." (PMID 26538832, 2015).
adenocarcinoma (4 papers, 2015 to 2022). A common cancer characterized by the presence of malignant glandular cells. "The protein levels of Hdac11 and Mmp3 were investigated by immunohistochemistry in normal, inflammation and adenocarcinoma colon tissues of the CAC mouse model, which was consistent with the qRT-PCR result." (PMID 35399729, 2022). "Hdac11 was dramatically decreased in the “inflammation-adenocarcinoma” tissues compared with the expression level in normal colorectal tissue, on the contrary, expression level of Mmp3 was increased." (PMID 35399729, 2022). "Here we confirmed those findings, and we observed a dramatic increase in Mmp3, Mmp10, and Mmp13 expression in CAC tissue relative to normal tissue; their expression was increased in dysplastic tissues and adenocarcinoma tissues and particularly in inflamed tissues." (PMID 25742789, 2015).
bacterial infection (4 papers, 2007 to 2024). "ADAMTS-5 and MMP-3 were identified as key enzymes involved in matrix catabolism during different phases of disc degeneration induced by the respective bacterial infections." (PMID 38297365, 2024). "The authors proposed that MMP-3 plays a role in host defense during tumorigenesis, a likely mechanism, given the impaired immunity to bacterial infection in similar KO animals." (PMID 17311017, 2007). "Meanwhile, the high-level stimulations of MMP3 and MMP9 in old hGFs subjected to bacterial infection may reflect a stress-induced aging phenotype in the gingiva." (PMID 27391467, 2016).
Neurologic Disease (4 papers, 2012 to 2025). "Also, data on the varicella zoster virus (VZV) neurologic disease in humans suggest involvement of multiple MMPs, with an increased concentration of MMP2 and to a lesser degree of MMP3 and MMP9 both in serum and CSF, as well as of MMP8 and MMP12 in CSF only." (PMID 40003967, 2025).
brain disorder (3 papers, 2008 to 2024). A disease affecting the brain or part of the brain. "In exploratory analyses, we found associations of ADAMTS13 activity with levels of VEGF, MMP-3, Tenascin-C, and TIMP-1, which might indeed indicate involvement in vascular remodelling, and in any case encourage further study of ADAMTS13 in relation to vascular (brain) disease and neurodegeneration." (PMID 29615758, 2018).
renal disease (3 papers, 2015 to 2024). "Early combination therapy with inhibitors of Mmp2, Mmp3 and Mmp9 significantly delayed the onset of proteinuria, while treatment after onset of proteinuria accelerated renal disease." (PMID 26673451, 2015). "Among serum biomarkers of renal involvement in AAV, the levels of MMP3 and thrombomodulin have been reported to be higher in patients with active renal disease than in those without." (PMID 28962592, 2017).
heart disease (2 papers, 2012 to 2024). "Of great interest are MMP-3 as a progression marker, MCP-3 as a urine marker, and IL-2 as a heart disease marker." (PMID 38476443, 2024).
intestinal bacterial infection (2 papers, 2014 to 2020). "In an DSS-induced mouse model of UC, expression of MMP-3 (stromelysin-1) and MMP-10 (stromelysin-2) increased in gut and intestinal ulcer tissues." (PMID 32486445, 2020).
musculoskeletal disease (2 papers, 2022 to 2024). "Some of the prominent MMPs involved in musculoskeletal disease are MMP-1, MMP-3, MMP-9, MMP-13, and MMP-14." (PMID 38790904, 2024).
osteoarthropathy (2 papers, 2021 to 2022). "However there are limited studies for the function of rs679620 in osteoarthropathy, the mechanisms of how the MMP-3 gene contributes to KBD are needed to be clarified, further studies should be expanded including the loci nearby rs679620." (PMID 34980041, 2022).
peripheral neuropathy (2 papers, 2006 to 2021). A disorder affecting the peripheral nervous system. "Although MMP-3 has been reported to be involved in the development of peripheral neuropathy, researchers believe that MMP-3 is not directly related to pain in patients with OA." (PMID 34276395, 2021).
gastrointestinal disease (1 paper, 2011). A disease that occurs in the gastrointestinal system, excluding the hepatobiliary system. "This curcumin mediated downregulation of MMP-3 and -9 levels in Hp-infected mice and cultured cells suggest its immense therapeutic potential against Hp associated gastrointestinal diseases." (PMID 21283694, 2011).
infectious disease (1 paper, 2022). A disorder directly resulting from the presence and activity of a microbial, viral, or parasitic agent in humans. "MMPs, including MMP-2, MMP-3, and MMP-8, are involved in the pathogenesis of infectious diseases." (PMID 36142454, 2022).
metabolic disease (1 paper, 2023). A congenital disorder (due to inherited enzyme abnormality) or acquired (due to failure of a metabolically important organ) disorder resulting from an abnormal metabolic process. "Matrix metalloproteinase-2 (MMP-2) and -3 (MMP-3), and osteopontin (OPN) are associated with adipose-tissue expansion and development of metabolic disease." (PMID 36648516, 2023).
MMP3 also shares sentences with these, for which no sentence is quoted: chronic periodontitis (12 papers); idiopathic pulmonary fibrosis (8); colorectal (3); connective tissue disorder (3); hemorrhagic stroke (3); multiple myeloma (3); polymyalgia rheumatica (3); renal cell carcinoma (3); acute lung injury (2); acute myeloid leukemia (2); acute myocardial infarction (2); benign tumor (2); biliary atresia (2); bone fracture (2); Brain Arteriovenous Malformations (2); chorioamnionitis (2); chronic rhinosinusitis (2); delirium (2); exfoliation syndrome (2); Fibroadenoma (2); gastric tumor (2); Infertility (2); Kawasaki disease (2); lumbar disc herniation (2); mental illnesses (2); neuroblastoma (2); osteosclerosis (2); peripheral arterial disease (2); primary biliary cholangitis (2); Proliferative retinopathy (2).
A further 135 diseases each share a sentence with MMP3 in 2 papers or fewer.